RFC1 (replication factor C subunit 1)
Diseases named in the same sentence as RFC1 in open-access papers (continued):
Sharing a sentence is not in itself a finding about the gene and the disease.
Down syndrome (3 papers, 2008 to 2024). "A common polymorphism (c.80A>G) in the gene coding for the reduced folate carrier (SLC19A1, commonly known as RFC-1) has been associated with maternal risk of the birth of a child with Down Syndrome (DS), but results are controversial." (PMID 23857226, 2013).
dysautonomia (3 papers, 2021 to 2022). An acute or chronic disorder, affecting the sympathetic or parasympathetic nervous system. "The phenotype across 70 RFC1-positive patients was mostly multisystemic (69%), including dysautonomia (62%) and bradykinesia (28%) (overlap with cerebellar-type multiple system atrophy [MSA-C]), postural instability (49%), slow vertical saccades (17%), and chorea or dystonia (11%)." (PMID 33495376, 2021).
episodic ataxia (3 papers, 2024 to 2025). "Furthermore, episodic ataxia is not a feature of RFC1‐related disease, in contrast to SCA27B." (PMID 38279833, 2024).
neural tube defect (3 papers, 2008 to 2026). A congenital defect characterized by failure of the neural tube to close completely; this results in the presence of openings in the brain or spinal cord. "Polymorphisms in folate transport genes have been implicated as risk factors for certain types of birth defects, and recent evidence from human epidemiological studies demonstrates an association between polymorphisms in RFC1 and increased risk for neural tube defects, and conotruncal heart defects." (PMID 18400109, 2008). "Folic acid supplementation and RFC1 (GG) genotype during pregnancy have gene-nutrition interactions on fetal neural tube defects (NTDs)." (PMID 36364804, 2022).
Nystagmus (3 papers, 2021 to 2025). Rhythmic, involuntary oscillations of one or both eyes related to abnormality in fixation, conjugate gaze, or vestibular mechanisms. "DBN occurred with cerebellar impairment in all 15 RFC1-positive patients, which was limited to the ocular motor system with typical cerebellar ocular motor signs (i.e., saccadic pursuit, dysmetric saccades, gaze-evoked nystagmus) in 5 patients (33%)." (PMID 38381176, 2024).
primary liver cancer (3 papers, 2016 to 2022). "Among the analysed polymorphisms, only the RFC1 80G>A polymorphism influenced the survival rate in primary liver cancers." (PMID 27936032, 2016). "The results of the present study demonstrate that the RFC1 80AA genotype is significantly associated with a poorer life expectancy in primary liver cancer patients." (PMID 27936032, 2016). "The observed association of RFC1 80G>A polymorphism with survival rate in primary liver cancer suggested to evaluate mCyt levels according to RFC1 80G>A genotypes." (PMID 27936032, 2016). "Among the polymorphisms analysed, the RFC1 80G>A (rs1051266) influenced the survival rate in primary liver cancers." (PMID 27936032, 2016). "The results of this study indicates that primary liver cancer patients carrying the RFC1 80AA genotype associated with low DNA methylation have a significantly poorer survival rate with a higher mortality risk, as compared with G allele carriers." (PMID 27936032, 2016). "The results suggest that RFC1 rs1051266 is associated with survival in primary liver cancer." (PMID 36497451, 2022). "Forty-seven primary liver cancer patients were genotyped for ten polymorphisms: DHFR 19bp ins/del, TS 2rpt-3rpt, MTHFD1 1958G>A, MTHFR 677C>T, MTR 2756A>G, MTRR 66A>G, RFC1 80G>A, SHMT1 1420C>T, BHMT 716 A>G, TC II 776C>G." (PMID 27936032, 2016). "Further investigations are certainly warranted to clarify the biological effect of RFC1 80G>A and the prognostic significance of PBMCs global DNA methylation assessment in primary liver cancers." (PMID 27936032, 2016). "RFC1 80G>A genotypes frequencies in primary liver cancer patients (n = 47)." (PMID 27936032, 2016). "The mechanism by which global DNA hypomethylation in the presence of the RFC1 80AA genotype may entail a poorer prognosis in patients affected by primary liver cancer remains to be explored." (PMID 27936032, 2016).
axonal neuropathy (2 papers, 2021 to 2025). Any nerve disorder affecting the axon of a nerve. "RFC1-positive consistently presented axonal neuropathy on nerve conduction studies (φc = 0.247, P < 0.001) and severely reduced sural nerve SNAP (R = − 0.199, P = 0.003)." (PMID 33884451, 2021). "Finally, the finding of a typical length-dependent axonal neuropathy, especially if pure sensory, should be followed up by a nerve ultrasound, and patients with abnormally small nerves should also have RFC1 genetic testing." (PMID 41322202, 2025).
brain infarcts (2 papers, 2015 to 2023). "RFC1 polymorphisms in human studies were associated with risk factors for ischemic stroke and silent brain infarcts." (PMID 37328777, 2023). "We selected three known RFC-1 polymorphisms (-43C>T, 80A>G, 696T>C) and investigated their relationship to cerebral infarction in the Korean population." (PMID 25659099, 2015). "In addition, we analyzed the correlation between homocysteine and folate levels after stratifying by sex, RFC-1 genotype, and ischemic stroke/silent brain infarction/control status." (PMID 25659099, 2015).
Charcot-Marie-Tooth disease (2 papers, 2021 to 2022). An inherited degenerative disorder involving the peripheral nerves. "These numbers suggest that RFC1 is among the three most common genetic causes of Charcot-Marie-Tooth disease in Finland together with PMP22 duplication and p.His123Arg in GDAP1." (PMID 34600502, 2021). "Taken together, RFC1 repeat expansion screening should also be recommended for the most common inherited peripheral neuropathy, hereditary motor and sensory neuropathy, or Charcot-Marie-Tooth disease." (PMID 36061987, 2022). "In addition, we found four patients with biallelic repeat expansion in RFC1 among patients with Charcot-Marie-Tooth disease." (PMID 34600502, 2021).
Cognitive impairment (2 papers, 2021 to 2025). Abnormal cognition is characterized by deficits in thinking, reasoning, or remembering. "The low prevalence of subjective EDS may reflect a chronic adaptation to longstanding sleep fragmentation or may be influenced by concomitant cognitive impairment associated with RFC1‐related disorders, potentially reducing awareness and perception of EDS." (PMID 40879541, 2025).
colon cancer (2 papers, 2025). "Additionally, RFC-1 expression was higher in the mucosa of right-sided or MSI-H colon cancers compared to left-sided or MSS/MSI-L cases, whereas the expression of both RFC-1 and PCFT was lower in right- than in left-sided tumors." (PMID 39998667, 2025). "The present study showed that the expression of ABCC3, MTHFD2, and RFC‐1 was lower, and TYMS higher, in rectal compared to colon cancer." (PMID 40357991, 2025). "In rectal cancer compared to colon cancer, ABCC3, RFC‐1, and MTHFD2 expression was significantly lower, while TYMS expression was higher." (PMID 40357991, 2025).
head and neck carcinoma (2 papers, 2012 to 2016). A carcinoma that arises from the head and neck region. "RFC1 80G allele was associated with an increased risk of head and neck carcinoma, whereas an increased risk of gastric and esophageal cancer was found in association with the RFC180AA genotype." (PMID 27936032, 2016). "Only our group evaluated the RFC1 A80G variant and its risk for head and neck cancer; we confirmed that the RFC1 80AG or 80AA genotypes were associated with an increased risk for these cancers, especially in males aged over 50 years that smoked cigarettes." (PMID 22392251, 2012).
hepatocellular carcinoma (2 papers, 2020 to 2022). A malignant tumor that arises from hepatocytes. "Human hepatocytes from transplanted mice showed a different gene expression profile compared to the hepatoma lines and expressed higher POLD2 and RFC1 transcripts." (PMID 32799415, 2020).
ischemic stroke (2 papers, 2015 to 2023). A stroke disorder caused by obstruction of blood flow to the brain, due to thrombotic (local blood clot formation) or embolic (due to a blood clot or other material traveling from another site) event. "Additional studies on the biological functions of RFC-1 are needed to fully understand the role of RFC-1 polymorphisms in controlling plasma homocysteine and folate levels in ischemic stroke and SBI patients." (PMID 25659099, 2015). "Previous reports, combined with our findings, suggest that the three RFC-1 polymorphisms work together to affect plasma levels of homocysteine and folate; these levels are related to risk of ischemic stroke and SBI." (PMID 25659099, 2015). "When we stratified ischemic stroke data by the size of the occluded vessel, we found an association between all three RFC-1 polymorphisms and both single and multiple SAOs." (PMID 25659099, 2015). "Furthermore, we propose that all three of the RFC-1 polymorphisms that we examined are genetic determinants for ischemic stroke risk in the Korean population." (PMID 25659099, 2015). "We used the polymerase chain reaction-restriction fragment length polymorphism (PCR-RFLP) method to analyze associations between the three RFC-1 polymorphisms, disease status, and folate and homocysteine levels in 584 ischemic stroke patients, 353 SBI patients, and 505 control subjects." (PMID 25659099, 2015). "Certain RFC-1 haplotypes also had a significant association with ischemic stroke." (PMID 25659099, 2015).
leukemia (2 papers, 2015 to 2018). A malignant (clonal) hematologic disorder, involving hematopoietic stem cells and characterized by the presence of primitive or atypical myeloid or lymphoid cells in the bone marrow and the blood. "As expected, knockdown of MLL-interactors with known essential functions, such as RFC1, SF3A3, or CCT3, led to growth inhibition in both MLL-fusion cells and MLL-wild-type leukemia cells." (PMID 29777171, 2018).
rectal cancer (2 papers, 2016 to 2025). A primary or metastatic malignant neoplasm that affects the rectum. "On the contrary, in patients affected by rectal cancer the RFC1 80AA genotype was associated with a more favourable prognosis." (PMID 27936032, 2016). "Specifically, ABCC3 and TYMS expression in rectal cancer were notably different in group 1 (p = 0.045 and p = 0.0056, respectively), whereas lower RFC‐1 expression was observed in both group 1 (p = 0.011) and group 2 (p = 0.0087)." (PMID 40357991, 2025).
Sensorimotor neuropathy (2 papers, 2021 to 2022). "Clinical presentation was associated with RFC1 expansion mutation status (φc = 0.381, P < 0.001): the RFC1-positive/biallelic AAGGGexp occurred in 21/40 (53%, CI 95% 36–68%) pure sensory CIAP, 10/56 (18%, CI 95% 9–30%) predominantly sensory and 3/138 (2%, CI 95% 0–6%) sensorimotor neuropathy cases." (PMID 33884451, 2021).
Sjögren syndrome (2 papers, 2021 to 2023). "A quarter of RFC1-positive patients had previously received an alternative diagnosis, including Sjögren’s syndrome, sensory chronic inflammatory demyelinating polyneuropathy and paraneoplastic neuropathy, while three cases had been treated with immune therapies." (PMID 33969391, 2021). "Positive RFC1 testing led to reclassification of 11 cases who had a previous alternative diagnosis, including sensory CIDP, Sjögren’s syndrome, paraneoplastic and metabolic neuropathy, and entailing three cases who had received unnecessary immune treatments." (PMID 33969391, 2021).
trisomy 21 (2 papers, 2015 to 2022). A chromosomal disorder consisting of the presence of an extra chromosome 21. "However, recent meta-analyses of those studies suggest that at least three of those polymorphisms, namely MTHFR 677C>T, MTRR 66A>G, and RFC1 80G>A, are likely to act as maternal risk factors for the birth of a child with trisomy 21, revealing also complex gene-nutrient interactions." (PMID 26161087, 2015). "Are the maternal gene variants MTHFR: c.665C>T, MTHFR: c.1286A>C, MTR: c.2756A>G, MTRR: c.66A>G, RFC1: c.80C>T and TCN2: c.776G>C and blood markers of the folate pathway important factors in assessing the risk of fetal trisomy 21 (fetal-T21)?" (PMID 35268281, 2022).
acquired ataxia (1 paper, 2024). A type of ataxia that is acquired during the lifetime of the individual. "It is important to screen patients diagnosed with other causes of acquired ataxia and SG as a small percentage were found to have RFC1 expansions." (PMID 37414537, 2024).
alopecia (1 paper, 2024). Hair loss usually from the scalp. "People with the RFC1 80AA genotype were shown to possess a greater prevalence of MTX-related hepatotoxicity and alopecia, while the TYMS 3R3R genotype was linked to a greater danger of bone marrow toxicity." (PMID 38311638, 2024).
ataxic disorders (1 paper, 2021). "Thus, sensory nerve degeneration seems to play a major and early role in RFC1-related ataxic disorders." (PMID 33969391, 2021).
autism (1 paper, 2021). Persistent deficits in social interaction and communication and interaction as well as a markedly restricted repertoire of activity and interest as well as repetitive patterns of behavior. "Further analysis revealed a significant increase in the reduced folate carrier (RFC1) G allele frequency among case mothers, but not among fathers or affected children, determining a significant increase of the risk of autism." (PMID 34440744, 2021).
autonomic neuropathy (1 paper, 2024). An inherited or acquired peripheral neuropathy affecting the autonomic nervous system. "Therefore, MND might belong to the expanding phenotypic spectrum of pathogenic RFC1 repeat expansions, particularly in those MND patients with additional features such as sensory and/or autonomic neuropathy, vestibular deficits, or cerebellar signs." (PMID 38916676, 2024).
brain tumour (1 paper, 2014). "For example, a decrease in expression of c-MYC, TIN2, DKC1, and RFC1 genes which are positive regulators of telomerase, was seen in MST-312 treated brain tumour cells." (PMID 25307264, 2014).
cervical cancer (1 paper, 2014). A primary or metastatic malignant neoplasm involving the cervix. "Our microarray data pointed out an increased level of BLM and RFC1 in the non-responding cervical cancers compared with the responding cancers." (PMID 24708616, 2014).
Charcot-Marie-Tooth neuropathy (1 paper, 2021). "Moreover, screening of 54 patients with Charcot-Marie-Tooth neuropathy revealed four additional patients with biallelic repeat expansion in RFC1, but none of them had cerebellar symptoms." (PMID 34600502, 2021).
chronic inflammatory demyelinating polyneuropathy (1 paper, 2023). "In this study RFC1 was examined in 240 patients with acute or chronic neuropathies, including 105 with Guillain-Barré syndrome or Miller Fisher syndrome, 76 with chronic inflammatory demyelinating polyneuropathy, and 59 with other types of chronic neuropathy." (PMID 37853169, 2023).
colon adenocarcinoma (1 paper, 2024). "The results enunciated correlation between RFC1 and RFC5 cluster of differentiation CD4 + T cell, macrophages, and neutrophils were correlated in COAD (Colon Adenocarcinoma) and READ (Rectal Adenocarcinoma) patients." (PMID 38504096, 2024).
colorectal adenocarcinoma (1 paper, 2024). The most common type of colorectal carcinoma. "However, RFC5 is targeted with associated miR-636 which is why we selected RFC1 and RFC5 as a prognostic marker for colorectal adenocarcinoma." (PMID 38504096, 2024). "We explored the potential mechanisms of RFC1 and RFC5 that mediated colorectal adenocarcinoma by focusing on potential microRNA." (PMID 38504096, 2024). "We believe that miR-26a-5p targeted RFC1 and miR-636 targeted RFC5 in the mismatch repair, DNA replication, and nucleotide excision repair pathway, play an essential role by mediating colorectal adenocarcinoma progression." (PMID 38504096, 2024). "MiR-26a-5p and miR-636 overexpression by competitively binding RFC1 and RFC5 mRNA 3’UTR leads to mismatch repair, DNA replication, and the nucleotide excision repair signaling pathway of colorectal adenocarcinoma." (PMID 38504096, 2024). "RFC1 and RFC5 were downregulated in colorectal adenocarcinoma and functionally suppressed the CRC." (PMID 38504096, 2024). "Some previous studies also showed that the miR-26a-5p and miR-636 targeted RFC1 and RFC5 in the mismatch repair, DNA replication, nucleotide excision repair pathway, mediated colorectal adenocarcinoma, and our results are consistent with those of a previous study." (PMID 38504096, 2024).
congenital heart disease (1 paper, 2013). A heart disease that is present at birth. "In this regard, maternal RFC-1 polymorphisms have been associated with congenital heart disease in the DS child." (PMID 23857226, 2013).
diabetes (1 paper, 2025). "The two Sāmoan RFC1 patients who had the NC_000004.12:g.39348425 AAAAG[n]AAGGG[n] motif expansion satisfied diagnostic criteria for diabetes on the basis of the repeat blood tests in this study, with HbA1c values of 45 and 46 mmol/mol (normal <40)." (PMID 41322202, 2025). "The other RFC1-positive participant with normal mean UL CSA and the RFC1-positive patient with the second largest CSA (4.9 mm2), both had HbA1c > 45 mmol/mol on this occasion, diagnostic of diabetes (having had borderline results in the past)." (PMID 41322202, 2025). "Two of the five RFC1-positive participants developed diabetes between their historic NCS and re-testing in this study." (PMID 41322202, 2025).
essential tremor (1 paper, 2022). A relatively common disorder characterized by a fairly specific pattern of tremors which are most prominent in the upper extremities and neck, inducing titubations of the head. "Unlike (AAGGG)exp of RFC1, (GGC)exp in NOTCH2NLC has been found rare in European patients with movement disorders, essential tremor, or leukoencephalopathy." (PMID 36061987, 2022).
Gait ataxia (1 paper, 2021). A type of ataxia characterized by the impairment of the ability to coordinate the movements required for normal walking. "Onset of gait ataxia in patients with RFC1 repeat expansions occurred at a median age of 53 years (range 32–72 years, IQR 49–60 years) and was earlier in patients with chronic cough (n = 46, age 50.3 ± 7.3 years) than without chronic cough (n = 19, age 61.7 ± 7.4 years, t test, p < 0.001)." (PMID 33495376, 2021).
gastroparesis (1 paper, 2025). Paralysis of the muscles of the stomach wall resulting in delayed emptying of the gastric contents into the small intestine. "RFC1-positive patients more commonly reported gastroparesis, constipation and impaired sweating of the feet, with higher impact scores for each." (PMID 41322202, 2025).
hereditary sensory neuropathies (1 paper, 2020). "In contrast to some other hereditary sensory neuropathies, patients with biallelic RFC1 expansions do not exhibit insensitivity to pain, with painless injuries, ulceration and amputations." (PMID 32040566, 2020).
Hutchinson-Gilford progeria syndrome (1 paper, 2022). "In the studies of Tang and Pennaneach, it is pointed out that RFC1 can promote cell survival after DNA damage through the retinoblastoma (Rb) pathway, which is related to Hutchinson-Gilford Progeria Syndrome (HGPS)." (PMID 35483337, 2022).
insomnia (1 paper, 2025). A sleep disorder characterized by difficulty in falling asleep and/or remaining asleep. "Obstructive sleep apnea, restless legs syndrome, periodic limb movements of sleep, and insomnia are common in RFC1‐related disease and should be actively investigated." (PMID 40879541, 2025). "Our findings demonstrate that OSA, RLS, and insomnia are highly prevalent among patients with RFC1‐related disorders when actively investigated." (PMID 40879541, 2025). "OSA, RLS, and insomnia are the most common sleep disorders in RFC1 pathology." (PMID 40879541, 2025).